IL20 (interleukin 20)
Diseases named in the same sentence as IL20 in open-access papers (continued):
Sharing a sentence is not in itself a finding about the gene and the disease.
osteoporosis (9 papers, 2015 to 2023). A condition of reduced bone mass, with decreased cortical thickness and a decrease in the number and size of the trabeculae of cancellous bone (but normal chemical composition), resulting in increased fracture incidence. "Our findings are in line with the already identified role of IL-20 in osteoporosis and the established association between the IL-22-IL-22R system and bone degradation in RA." (PMID 26968800, 2016). "The in vivo study revealed that IL-20 was associated with bone formation in the model of bone fracture and osteoporosis." (PMID 27075747, 2016). "Inhibition of IL-20 may repress osteoclast activity to ameliorate bone loss, such as in osteoporosis." (PMID 36835229, 2023). "Some studies have shown that IL-20 plays important roles in osteoporosis and bone loss-related diseases; moreover, studies in ovariectomised mice have shown that anti-IL-20 antibodies can prevent bone resorption by blocking osteoclast formation and inducing osteoblast formation." (PMID 34122555, 2021). "We previously observed that concentration of IL-20 in serum was obviously higher in osteopenia and osteoporosis patients compared to healthy ones, suggesting IL-20 might involve in the bone loss." (PMID 29690863, 2018). "Risedronate, as a clinical drug to target osteoporosis, partly decreased the level of IL-20 and inhibited IL-20-induced osteoclast formation." (PMID 36835229, 2023). "Studies have shown that the median serum levels of IL-20 in patients with osteoporosis and osteopenia are 209.5 pg/mL and 181.3 pg/mL, respectively; however, healthy people exhibited a median serum level of 15.38 pg/mL." (PMID 34122555, 2021). "The result indicates that blocking of IL-20’s function is a potential way to treat osteoporosis and bone fracture, with more advantages than current drugs on the market." (PMID 29690863, 2018). "IL-20 and sclerostin are positively correlated in the serum of bone fracture, osteopenia, and osteoporosis patients." (PMID 29690863, 2018). "The anti-IL-20 monoclonal antibody treatment has a therapeutic potential in several experimental disease models including ovariectomy-induced osteoporosis, cancer-induced osteolysis, and bone fracture." (PMID 29690863, 2018). "In the context of arthritis, it is intriguing that IL-20 has also been reported as a driver of osteoporosis and that both IL-19 and IL-24 had roles in a rat model of bone resorption." (PMID 26968800, 2016). "The findings were similar in patients with osteopenia (r = 0.631) and osteoporosis (r = 0.682), which suggested that IL-20 may be involved in osteoblastogenesis by regulating sclerostin, and associated with metabolic bone diseases." (PMID 27075747, 2016). "Therefore, the strategy of blocking IL-20 may help us fight against osteoporosis." (PMID 29690863, 2018). "Moreover, risedronate, an anti-osteoporosis drug, decreased the distance of tooth movement in OVX rats and simultaneously decreased the number of IL-20-positive cells and TRAP-positive osteoclasts." (PMID 36835229, 2023).
Arthritis (8 papers, 2015 to 2022). Inflammation of a joint. "Recent studies demonstrated that blocking of IL-19 or IL-20 reduced bone loss and ameliorated collagen-induced arthritis in rat, suggesting that IL-19 and IL-20 are important proinflammatory molecules in bone or joint related diseases." (PMID 30250404, 2018). "Cytokines level (members of IL-1 family, IL-6 and its receptor, IL-17, IL-20, IL-21, and IL-23) increases in early stages of arthritis and decreases during regression of inflammation." (PMID 35061737, 2022). "A recent study showed that a broad blockade of IL-20 subfamily (including IL-19, IL-20, and IL-24) by using soluble-IL-20R2-Fc fusion protein significantly ameliorated the severity of arthritis in CIA model." (PMID 29690863, 2018). "The anti-IL-20 mAb 7E treatment significantly ameliorated the arthritis symptoms and prevented CIA rats from bone destruction." (PMID 29690863, 2018). "Supporting tissue homestatic properties in arthritis, IL-20 and IL-24 have been shown to increase osteoblast mineralization and are associated with chronic changes in the lumbar spine in SpA." (PMID 30319661, 2018). "Anti-IL-20 monoclonal antibody (mAb) 7E significantly improves the symptoms of arthritis through reducing thickness and swelling of hind-paw, suppressing bone destruction, and inhibiting the production of proinflammatory cytokines in synovial tissue." (PMID 29690863, 2018). "Expression of IL-19, IL-20, and IL-24 in both monocytes/macrophages and fibroblast-like synovial cells has been reported in arthritis." (PMID 26968800, 2016). "Anti-IL-20 mAb reduced the severity of arthritis in murine models of surgery-induced OA." (PMID 28426699, 2017). "Moreover, anti-IL-20 monoclonal antibody (7E) treatment or electroporating soluble IL-20R1 plasmid DNA into rats with collagen-induced arthritis (CIA) reduced the arthritis severity, which suggested that IL-20 could be the therapeutic target for RA treatment." (PMID 28426699, 2017). "Therefore, targeting IL-20 may significantly improve the severity of arthritis." (PMID 29690863, 2018). "Serum concentrations of OPG and IL-20 were significantly higher both in the psoriatic patients without arthritis and in the PsA patients than in the control group (p = 0.05 or less)." (PMID 26146462, 2015). "In our study, IL-20 was significantly higher in both psoriatic patients without arthritis and PsA patients in comparison with the control group." (PMID 26146462, 2015).
bladder cancer (8 papers, 2012 to 2024). "This study suggests the presence of specific inflammatory cytokine (IL-5, IL-20, and IL-28A)-mediated association in bladder cancer development." (PMID 22962576, 2012). "Additionally, we found that the inflammatory factor IL-20 and one of its receptors, IL-22RA1, both associated with monocytes, are risk factors for bladder cancer." (PMID 39450166, 2024). "Furthermore, inflammatory factors IL-20, IL-22RA1, and Eotaxin were significantly associated with an increased risk of bladder cancer." (PMID 39450166, 2024). "Interleukin-20 induces the up-regulation of p21(WAF1) protein expression, which in turn causes nuclear factor (NF-B) to activate by promoting the migration of bladder cancer cells via ERK-mediated MMP-9 protein production." (PMID 38172584, 2024). "This evidence underscores the ability of IL-20 and IL-22RA1 to enhance bladder cancer migration, invasion, and development." (PMID 39450166, 2024). "In bladder cancer cells, MAPKs/AP-1 activation is mediated by interleukin-20 and also enhances cell migration inhuman bladder cancer T24 and U5637." (PMID 25402510, 2015). "Our data showed that IL-5, IL-20, and IL-28A stimulated the migration and invasion of bladder cancer cells." (PMID 22962576, 2012). "The present results indicate that transcription factors NF-κB and AP-1 are the main factors for MMP-9 induction in response to IL-5, IL-20, and IL-28A in bladder cancer cells." (PMID 22962576, 2012). "To this end, we performed an electrophoretic mobility shift assay (EMSA) using nuclear extracts of bladder cancer cells induced by IL-5, IL-20, and IL-28A." (PMID 22962576, 2012). "Because signaling for cytokines primarily activates the Jak/Stat and MAPK signal transduction pathways, we next investigated the signaling cascades induced by IL-5, IL-20, and IL-28A in bladder cancer cells." (PMID 22962576, 2012). "Our results from bladder cancer cells indicate that IL-20 induced activation of ERK1/2 and Jak1, Jak2, Jak3, Stat1, Stat2, and Stat5." (PMID 22962576, 2012). "In the present study, the up-regulation of IL-20 was not only shown in MIBC tissues but also produced by bladder cancer cells." (PMID 22962576, 2012). "Among the 10 up-regulated molecules examined, the capacity for both wound-healing migration and invasion was enhanced in response to IL-5, IL-20, and IL-28A in bladder cancer cell lines (253J and EJ cells), compared with untreated cells." (PMID 22962576, 2012). "In addition, our findings highlight the role of IL-20 and IL-22RA1, a component of its receptor, in bladder cancer development." (PMID 39450166, 2024). "IL‐20 could also induce bladder cancer cell migration by activating the ERK‐mediated NF‐κB pathway, and promoting MMP‐9 production subsequently." (PMID 33900049, 2021). "Finally, activation of MAPK and Jak-Stat signaling was observed after the addition of IL-5, IL-20, and IL-28A to bladder cancer cells." (PMID 22962576, 2012). "Among the genes and proteins examined, we observed that IL-5, IL-20, IL-28A, and their receptors produced by bladder cancer cells induced migration, invasion, transcription factor-mediated MMP-9 expression, and activation of signaling pathways, such as the MAPK and Jak-Stat pathways." (PMID 22962576, 2012). "Results from the present study showed expression of IL-20 and IL-20R1 in bladder cancer cells." (PMID 22962576, 2012). "IL-5, IL-20, and IL-28A may thus be major molecules that characterize the migration and invasiveness of TCC, as well as the development of bladder cancer associated with disease progression." (PMID 22962576, 2012). "In addition, we also identified that MAPK and Jak/Stat signaling are activated in bladder cancer cells following treatment with IL-5, IL-20, and IL-28A." (PMID 22962576, 2012). "Thus, our results are the first to suggest that IL-5, IL-20, and IL-28A act as novel factors of migration and invasion in bladder carcinoma cells." (PMID 22962576, 2012).
bladder cancer (continued). "Furthermore, we reveal the involvement of two circulating inflammatory factors in bladder cancer at the same screening criteria (p<0.01), respectively as the level of Eotaxin (CCL11, OR: 1.26, 95% CI 1.06-1.49, p=0.0075) and IL-20 (OR: 1.40, 95% CI 1.09-1.82, p=0.0097) which are all risk factors." (PMID 39450166, 2024). "Other studies have shown that IL–20 upregulated invasion-related genes like MMP–9 and MMP–12, which degrade extracellular matrix in breast and bladder cancers." (PMID 26440411, 2015). "However, AKT activation was not influenced in IL-5-, IL-20-, and IL-28A-treated bladder cancer cells." (PMID 22962576, 2012). "Unexpectedly, the results of the present study showed that 3 kinds of cytokines (IL-5, IL-20, and IL-28A) correlate with metastatic potential without altering cell proliferation, which results in bladder cancer cell migration and invasion through MMP-2 and MMP-9 expression." (PMID 22962576, 2012).
liver fibrosis (7 papers, 2015 to 2024). "Taken together, the current work confirms that IL-20 is a pathogenic cytokine that is upregulated during liver fibrosis." (PMID 38699038, 2024). "Several animal experiments showed that blockade of IL-20 can effectively attenuate inflammation and ameliorate the severity of liver fibrosis." (PMID 32028746, 2020). "Intriguingly, inhibition of the IL-20 axis in carbon tetrachloride induced liver injury reduces diseases severity by restoring hepatocyte proliferation and prevents liver fibrosis by inducing high expression levels of TMP-1." (PMID 26162095, 2015). "Treatment with neutralizing antibody against IL-20 or IL20RA diminishes the CCl4-induced liver fibrosis in mice." (PMID 26199463, 2015). "Similar to IL-10, elevated level of IL-20 was found in hepatocytes and hepatic stellate cells of patients suffering from liver fibrosis." (PMID 26199463, 2015). "We confirmed that there were no expression changes associated with liver fibrosis in the mRNA expression levels of IL-20, IL-24, and IL-20R1." (PMID 37509702, 2023). "IL-20 is increased in mice with CCl4-induced liver fibrosis." (PMID 32028746, 2020). "The most studied members of the IL-10 family related to liver fibrosis are IL-10, IL-20, and IL-22." (PMID 26199463, 2015). "In addition, IL-20 was found to induce liver fibrosis by upregulating Col I production in rat HSCs." (PMID 38699038, 2024). "Also IL-20 KO mice are less sensitive against CCl4-induced liver fibrosis." (PMID 26199463, 2015). "IL-20 acts as a potential target for liver diseases by combining its own receptors and signaling pathways to play a series of biofunctional regulatory roles in viral hepatitis, NAFLD, HCC and liver fibrosis." (PMID 38699038, 2024).
autoimmune disease (6 papers, 2015 to 2026). A disorder resulting from loss of function or tissue destruction of an organ or multiple organs, arising from humoral or cellular immune responses of the individual to their own tissue constituents. "The levels of IL-20, which is expressed by multiple cell types (i.e., monocytes, skin keratinocytes) and implicated in autoimmune diseases pathogenesis, were found to be reduced in the involved skin of SSc patients by Kudo and collaborators in 2014." (PMID 36059817, 2022). "Cytokines interleukin-17 (IL-17) and interleukin-20 (IL-20) play important roles in inflammatory processes and autoimmune diseases." (PMID 42017161, 2026). "This study focused on IL-20 due to its pro-inflammatory role in autoimmune diseases and because this cytokine requires a high-sensitivity assay for detection in SF where limited sample material is available." (PMID 26268325, 2015). "We chose IL-20 as a model cytokine due its widely described role in the pathogenesis of several autoimmune diseases, including psoriasis and RA." (PMID 26268325, 2015). "This may also suggest that blocking the IL-20 pathway might be effective in the treatment of multiple autoimmune diseases." (PMID 27799070, 2016).
asthma (5 papers, 2019 to 2023). "IL-20 has also been suggested to be involved in airway remodelling in asthma." (PMID 30834110, 2019). "IL-24 shares two heterodimeric receptors (IL-20R1 and IL-20R2) with IL-19 and IL-20, and whether these receptors have similar or redundant biological effects on airway remodeling in airway epithelial cells or asthma models remains unclear and needs further examination." (PMID 36100847, 2022).
colitis (5 papers, 2022 to 2024). Inflammation of the colon. "Moreover, reports of IL-20 receptors increasing in colitis are accompanied by a loss of goblet cells, suggesting that absorptive epithelial cells are the main target of IL-20, potentially along with immune cells." (PMID 36613621, 2022). "Since other cytokines such as IL-20 and IL-24 also signal through IL-22Ra1, we used Il22−/− mice and observed that these mice were more susceptible to DSS-induced colitis as compared to wild-type controls." (PMID 38733584, 2024). "Previous reports have demonstrated that the epithelial cell expression of IL-20RB and IL-20 protein are increased in colitis." (PMID 36613621, 2022). "These indicate the possible potential role of IL-20 in active colitis, which also could be beneficial in exogenous delivery to promote fast recovery." (PMID 36613621, 2022). "In addition, we evaluated the therapeutic potential of using recombinant IL-20 in the acute and spontaneous models of colitis." (PMID 36613621, 2022). "To assess whether IL-20 activates ERK1/2 in colitis, we utilized the Winnie mouse model of colitis, which carries a missense Muc2 gene mutation which results in an epithelial cell defect." (PMID 36613621, 2022). "By using chemical-induced (dextran sodium sulphate; DSS) colitis and a spontaneous model of colitis (Winnie mice), we assess whether recombinant IL-20 treatment is beneficial in reducing/improving pathology." (PMID 36613621, 2022). "Expression of NF-κB, TLR4, Myd88, and downstream molecules such as TNF-α, IL-6, and IL-1β was effectively reduced by SGP-H, which improved the secretion of anti-inflammatory cytokines including IL-20 and IL-10 in the colon tissue and serum of DSS-induced colitis mice." (PMID 37836386, 2023).
diabetes (5 papers, 2015 to 2025). "In diabetes, HSCs can be activated by liver injury and systemic cytokines, like IL-17 and IL-20, enhancing CCL2-mediated monocyte recruitment." (PMID 40362271, 2025). "Moreover, IL-20, which is a pro-inflammatory cytokine that has been implicated in renal disease, is upregulated in diabetic animal models and human patients, although its direct association with diabetes remains unclear." (PMID 40333882, 2025). "Deficiency in IL-20R1 and blockade of IL-20 with anti-IL-20 mAb 7E reduced UACR, mesangial cell expansion, and podocyte apoptosis in experimental diabetes." (PMID 32471207, 2020). "We previously reported that IL-20 was upregulated in the serum of patients with diabetes mellitus." (PMID 32028746, 2020).
ischemic stroke (5 papers, 2015 to 2023). A stroke disorder caused by obstruction of blood flow to the brain, due to thrombotic (local blood clot formation) or embolic (due to a blood clot or other material traveling from another site) event. "Furthermore, a randomized controlled study of ischemic stroke patients demonstrated that tumor necrosis factor-α and the interleukins (IL), such as IL-1β, IL-6, and IL-20, were associated with inflammation in ischemic stroke." (PMID 37533068, 2023). "IL-20 may be associated with the increased IL-6 levels in serum after ischemic stroke." (PMID 35173738, 2022). "The upregulation of IL-20 on glial pro-inflammatory cytokines and chemokines (may cooperate with IL-1β to promote inflammatory activity) is associated with inflammatory response and brain damage after ischemic stroke." (PMID 35173738, 2022). "In conclusion, IL-20 is a novel hypoxia response factor that is upregulated in gliocyte after experimental ischemic stroke and mediates cell proliferation, signal transduction, and cytokine production." (PMID 35173738, 2022). "These suggest that IL-20 is related to the pathogenesis of cerebral ischemia, and IL-20 antagonists may have clinical therapeutic effects on ischemic stroke." (PMID 35173738, 2022).